MMP9 (matrix metallopeptidase 9)
Diseases named in the same sentence as MMP9 in open-access papers (continued):
Sharing a sentence is not in itself a finding about the gene and the disease.
tumor (continued). "We demonstrated that CREB3 could bind to the promoter of c-Jun and subsequently enhance the expression of mmp9, an important biomarker for tumor metastasis, and Bcl-2, a pivotal antiapoptotic molecule in the plasma." (PMID 30940151, 2019). "We also showed that the primary tumor could also provide MMP9 that could be responsible for invasion and metastasis." (PMID 31727800, 2019). "Studies have shown that MMP9 can damage the integrity of the extracellular matrix, which opens an important channel for the invasion of tumor cells and accelerates the formation of tumor deterioration." (PMID 31346317, 2019). "Thus, we postulate that MMP-9 limits anti-tumor response, at least in part, through degradation of tumoral CXCR3 ligands, resulting in suboptimal trafficking of Th1 cells to tumors." (PMID 30500835, 2018). "MMPs, also considered as markers of epithelial-to-mesenchymal transition (EMT) (especially MMP-2 and MMP-9), render tumor cells able to metastasize in distant organs by breaking down the basement membrane, thus allowing cancer cells to enter the lymphatic or blood vessels." (PMID 30301152, 2018). "For example, N1 neutrophils produce higher levels of TNFα, NO, and ROS, and are able to kill cancer cells whereas N2 neutrophils express high levels of C-X-C chemokine receptor type 4 (CXCR4 or CD184), gelatinase B/MMP9, among other markers, and act as mediators of tumor progression." (PMID 29719508, 2018). "Notwithstanding the relatively limited MMP-9 expression observed in these tumors as compared to human disease, anti–MMP-9 antibody treatment significantly reduced tumor growth as compared to IgG control (56% vs 335% tumor volume increase, respectively; p = 0.0005)." (PMID 30500835, 2018). "Furthermore, we found that MKRN2 inhibited cell migration and invasion in NSCLC cells by regulating the expression of RhoA/ROCK1 and MMP9, thereby influencing the malignant behavior of tumor cells." (PMID 30103781, 2018). "The amount of the active form of MMP-9 in stromal cells and tumour cells may differ, which could account for the differences in clinical outcomes." (PMID 30142200, 2018). "Besides, treatment of BA treatment of mice with BA inhibited the expression of MMP-2, MMP-9 and P-Stat3 in 4T1 tumor tissues." (PMID 29423083, 2018). "This activates AP-1-driven transcription of mmp9 that promotes tumour dissemination." (PMID 29570727, 2018). "MMP-9 is known to contribute to tumor progression including angiogenesis and invasion." (PMID 29758011, 2018). "An inhibitor of MMPs, including MMP7 and MMP9, was shown to suppress tumour metastasis." (PMID 29631554, 2018). "We previously found that EGCG inhibited SW780 tumor growth by down-regulation of NF-κB and MMP-9." (PMID 29552308, 2018). "The same treatment group had a larger proportion of CD4+ T and CD8+ memory/effector T cells (CD3+CD4+CD44+ and CD3+CD8+CD44+, respectively) among tumor-infiltrating leukocytes, suggesting that the anti–MMP-9/anti-PDL1 combination promotes a functional T cell–mediated antitumor response." (PMID 30500835, 2018). "Indeed, exosomes expressing HSP72 and HSP105 can trigger a TLR2- and TLR4-dependent IL-6 release from conventional DCs and a consequent MMP9 expression in tumor cells with enhanced invasion and metastasis." (PMID 30200242, 2018). "In addition, our results indicate that knockdown of TIGAR reduces the expression of MMP2 and MMP9, which play important roles in the formation of tumor microenvironments and in the promotion of cancer progression and metastasis." (PMID 29753331, 2018). "Moreover, TIPE2 suppressed tumor invasiveness by inhibiting Rac1, leading to decreased expression of uPA and MMP9." (PMID 30186591, 2018). "There is a possibility that by decreasing Endothelin levels, Nintedanib was also effective in decreasing MMP-9 expression, which could possibly lead to decreased tumor invasiveness and metastasis." (PMID 29934570, 2018).
tumor (continued). "These researchers also observed that the administration of 5 × 10 Gy to the subcutaneous tumor in the thigh enhanced the MMP9 level, stimulated entry of cancer cells into the circulation and increased the number of pulmonary metastasis, whereas 2 × 30 Gy reduced these parameters." (PMID 30134800, 2018). "Interestingly, the expression of MMPs, and in particular the release of pro-MMP-9, is promoted by tumor-derived CXCL12 in an autocrine fashion." (PMID 30591657, 2018). "High expression of MMP-2 and MMP-9 can enhance the invasion and metastasis ability of tumour cells." (PMID 29751513, 2018). "Matrix metalloproteinase 2 (MMP2) and MMP9 possess ability to hydrolyze components of the basement membrane, and thus could promote tumor metastasis." (PMID 29880874, 2018). "In previous studies, MMP-9 was reported to be overexpressed in aggressive tumours." (PMID 30142200, 2018). "As we could not reliably detect these chemokine breakdown products in the murine tumor model, we performed an analysis of human chemokine processing by human MMP-9." (PMID 30500835, 2018). "The study also provides a clue about the communication between the EGFR/AR axis and MMP-9, which might be a crucial component of tumor dissemination and establishment at the metastatic sites." (PMID 30134822, 2018). "We hypothesized that intact FBLN5 may either inhibit tumor cell-derived MMP-9 or inhibit malignant cell adhesion to native ECM components and thereby protect from local spread of the disease." (PMID 29581841, 2018). "On this basis, we assessed whether XAF1 inhibits tumor cell migration and invasion by blocking p65/RelA-mediated MMP9 transcription through IRF-1 induction." (PMID 30042418, 2018). "Moreover, primary tumor cells specifically induced MMP-9 expression in lung macrophages and endothelial cells by the action of VEGF receptor-1 (VEGF-R1)." (PMID 30597969, 2018). "An abundance of MMP-9 facilitates tumor progression and invasion." (PMID 30445746, 2018). "Besides, Rao and coworkers demonstrated that a cooperation between uPA/uPAR and MMP-9 is required for breaching of the vascular wall, a rate-limiting step for intravasation, and consequently for tumor progression and metastasis." (PMID 29615071, 2018). "The mobilisation of various growth factors from tumour interstitium by active MMP9 might be the major mechanism leading to rebound tumour angiogenesis, resistant to vascular disruption therapies." (PMID 29367702, 2018). "MMP-9 is present in a wide variety of tumor types at the mRNA and protein levels." (PMID 30500835, 2018). "PLT NPs could inhibit the adhesion between tumor cells and platelets and the production of MMP‐9 to inhibit different phases of the metastasis cascade." (PMID 30479911, 2018). "The sustained MMP-9 expression is responsible for the invasive nature of tumor cells." (PMID 30149671, 2018). "Moreover, DGCR5 also lead to significant expression in migration and invasion‐related marker MMP‐3 and MMP‐9 in tumor samples." (PMID 29790668, 2018). "Therefore, the activity or amount of MMP-2 and MMP-9 in tumor tissues is often used as tumor indicator in terms of activity and severity." (PMID 30558243, 2018). "Furthermore, NETs have been reported to highly express neutrophil derived matrix metalloproteinase (MMP)-9, which plays critial roles on degradation of extracellular matrix to facilitate tumor invasion." (PMID 29330531, 2018). "Moreover, expression and production of the tumour-promoting factors MMP-9, RANTES, and VEGF, which are highly enhanced in TAMs, was significantly suppressed by deoxyschizandrin treatment." (PMID 29342940, 2018). "Similarly, reductions in protein expression of MMP-9 were also seen, with values of 40.1% (p < 0.05), 51.6% (p < 0.05), and 55.4% (p < 0.05), respectively, when compared with the tumor control group." (PMID 29794990, 2018).
tumor (continued). "Nevertheless, a dissociation between survival and MMP-9 is thought to derive from incredible advance of technical surgical procedures, chemotherapy, hormonal therapy, and the number of immune cells raised against tumour cells." (PMID 30142200, 2018). "The expression change of HNF4α might be positively correlated with E-cadherin, and negatively with MMP9 in IL-23 mediated tumor progression." (PMID 29983862, 2018). "Furthermore, in CP-treated cells, we detected the decreasing expression of MMP-2 and MMP-9, which are necessary for tumor metastasis." (PMID 30149677, 2018). "Moreover, MMP-9 can enhance the heterogeneous adhesion of tumor cells via activating related cytokines and then increasing the expression of intercellular adhesion molecule." (PMID 30046339, 2018). "The difference in the prognostic value of MMP-9 expression in stromal and tumour cells might reflect the presence of active and inactive forms of MMP-9." (PMID 30142200, 2018). "Moreover, antiapoptotic factor Bcl-2 and the migration related protein MMP-9 were significantly increased in ALDH+ cells compared with ALDH− tumor cells." (PMID 29914196, 2018). "Therefore, inhibiting MMP-9 expression can interfere with the tumor cell proliferation, migration, heterogeneous adhesion, and ECM and BM degradation." (PMID 30046339, 2018). "MMP-7/9/12 (tumor-associated macrophages), MMP-9 (embryonic cells), MMP-11 (adipose cells) and a myriad of MMPs are known to interact with CAFs, while also causing a transition of mature stromal cells to tumor cells." (PMID 29881724, 2018). "Moreover, the oral administration of KPS-A in mice inoculated with YD10B OSCC cells led to substantial inhibition of tumour growth and the expression of HuR, MMP-9, and TIMP-1." (PMID 29619127, 2018). "Recent studies demonstrated that MMP-9 could be involved in natural killer (NK) cell dysfunction by promoting tumour immune avoidance." (PMID 30142200, 2018). "In addition, the MMP-9 mRNA level was significantly risen in patients with higher tumor stages (III/IV) compared to those with lower stages (I/II) (P = 0.011); also, in patients with lymphovascular invasion compared to those without invasion (P = 0.003)." (PMID 30509240, 2018). "Tumor weight in the anti–MMP-9–treated group was reduced compared to the control." (PMID 30500835, 2018). "It is known that the uPA and MMP9 are important Rac1 downstream effectors that are responsible for degrading the extracellular matrix components, which is essential for the invasiveness of tumor cells." (PMID 30186591, 2018). "MMP-2 and MMP-9 can degrade type IV collagen, which contributes to tumor invasion and metastasis." (PMID 29977159, 2018). "In addition, the stemness marker proteins CD44, Oct-4, Nanog, as well as Bcl-2 and MMP-9 expression levels of ALDH+ cells were upregulated compared with the original tumor cells, indicating that they have certain stem cell characteristics." (PMID 29914196, 2018). "Regarding MMP-9, higher activity in tumor tissues is reported in NSCLC than in SCLC33." (PMID 30018308, 2018). "However others, employing the human choriocarcinoma cell line, JEG-3, showed that IL-12 reduced the mRNA and protein expression levels, and also the enzymic activity of both MMP-2 and MMP-9, leading to suppression of tumour cell motility and invasion." (PMID 29555826, 2018). "Therefore, an exogenously administered tumor-penetrating nanosensor with an MMP-9 peptide substrate in its surface has been created." (PMID 30237810, 2018). "Gga-miR-130b-3p inhibited the expression level of MMP2 and MMP9, which indicates that this miRNA may be involved in MD tumor transformation through suppressing cell invasion." (PMID 29849932, 2018). "MMP-9 may regulate tumor invasion and metastasis, and promote antitumor immune dysfunction by activating TGF-β." (PMID 30500835, 2018).
tumor (continued). "In addition, our previous study elucidated that EGCG was effective in inhibition SW780 cell proliferation and migration, and EGCG inhibited SW780 tumor growth by down-regulation of NF-κB and MMP-9." (PMID 29552308, 2018). "MMP9 promotes tumor metastasis by facilitating tumor cell migration and invasion." (PMID 30429233, 2018). "Additionally, MMP7 is able to convert proMMP2 to active MMP2 and proMMP9 to active MMP9 thereby facilitating macrophage-tumor-stromal cell cross-talk." (PMID 29581841, 2018). "To determine whether andrographolide regulates the expression of MMPs, we then measured MMP-2 and MMP-9 levels in the supernatant of in vitro cultured tumor cells by using gelatin zymography analysis." (PMID 30359388, 2018). "The tumor tissue was excised and subjected to anti-MMP9 staining." (PMID 29844876, 2018). "Additionally, human GBM samples express high levels of MMP-2 and MMP-9 as compared to normal brain tissues, and these levels increased with tumor progression." (PMID 30441761, 2018). "Over the last decades it has been extensively reported that tumor associated macrophages are able to promote tumor cell migration thought secretion of matrix-remodeling proteins, cytokines and chemokines (e.g. MMP-2, MMP-9, TNF-α, VEGF, TGF-β, EGF)." (PMID 29728948, 2018). "A series of studies demonstrated that enzymes such as MMP-2, MMP-9, and uPA generated by tumor cells participated in the proteolytic degradation of the EMC, disrupted the paratumoral anatomy, advanced tumor cells' further penetration, and led to PNI of SACC, eventually." (PMID 30430081, 2018). "MMP-9 expression was heterogeneous, among and within specific tumor types." (PMID 30500835, 2018). "In addition, expression of vascular leakage-related mediators and matrix-degrading enzymes such as MMP-9 is increased in TEMs, which facilitates invasive tumor growth and metastasis." (PMID 29946226, 2018). "Moreover, the data suggested that IL-6/JAK2/STAT3 pathway contributes to tumor invasion by elevating MMP-9 expressions." (PMID 32922863, 2018). "Furthermore, HuR has also been reported to interact with oncogenes (i.e., c-myc in OSCCs) as well as molecules regulating tumour invasiveness (i.e., MMP-9 in OSCCs)." (PMID 29619127, 2018). "While MMP2- and MMP9-deificent embryonic fibroblasts co-injected with SCCA cells demonstrated suppressed tumor growth in a mouse model of cancer, an enhancement of tumor establishment was noted, suggesting that CAF are sufficient, but not necessary, for tumor development." (PMID 28966935, 2017). "Deletion of MMP9 in myeloid cells abolishes their ability to promote tumor growth." (PMID 28423685, 2017). "Interestingly, we found increased MMP9 gene copy number in the two metastases of patient D2 when compared with the matched primary sample, as well as intra-tumour heterogeneity of MMP9 along the proximal–distal axis." (PMID 28120820, 2017). "TIMP-free MMP-9 release can also promote tumor growth and metastasis." (PMID 28149530, 2017). "One member of this family, MMP-9, is also an important promoter of tumor invasion." (PMID 28591697, 2017). "It would also be important to determine whether tumor-fibroblast interactions regulate other pro-angiogenic factors in the MMP9-driven angiogenesis." (PMID 28423685, 2017). "However, significant increase in TGF-β1, MMP-2 and MMP-9 gene expression was noted in tumor cells from high metastatic lesions in the lungs." (PMID 28819116, 2017). "MMP-9 expression was observed in tumor cells and tumor-infiltrating neutrophils." (PMID 28505114, 2017). "Indeed, hypoxic tumor areas are characterized by the presence of VEGFR1high macrophages that actively secrete MMP9 and thus promote angiogenesis and invasion." (PMID 29212030, 2017). "MMP2, MMP3, MMP9, uPA and Cathepsin B play critical roles in tumor invasion and metastasis." (PMID 29137230, 2017). "Exo70 may be involved in tumor invasion by regulating MMP-9 secretion through synergistic reaction with CTTN in HCC26." (PMID 28698570, 2017).
tumor (continued). "Genetic ablation of MMP-9 prevents the initiation of tumor angiogenesis in mouse models." (PMID 28388546, 2017). "Therefore, to understand the precise mechanism of tumor suppressive role of MMP9 in CAC, it is very important to know which MMP9 ‘epithelial-derived’ or ‘neutrophil-derived’ is involved." (PMID 27861153, 2017). "Therefore, it is possible that ANXA13-mediated activation of AKT and MMP-9 plays a pivotal role in tumor cell invasion and metastasis in CRC." (PMID 28423508, 2017). "According to our results, wogonoside could suppress tumor metastasis through inhibition of primary tumor invasion by increasing the expression of E-cadherin and decreasing the expression of MMP-9, vimentin and Twist1." (PMID 28774312, 2017). "So, we evaluated the expression of MMP9 in ESCCs, found that MMP9 was mainly expressed in stroma cells, only a small section of tissue showed tumor cells staining, and MMP9 expression was much higher in ESCCs than in CANs, particularly in the strong MMP9 staining positive cases." (PMID 28423526, 2017). "Gelatinases MMP-2 and MMP-9 are responsible for Fibulin-2 degradation in these tumor cells." (PMID 28099917, 2017). "In addition, tumor expression of IL-6, MMP-9 and ALDH1A1 was decreased (P < 0.05) in mice treated with pHLIP-PNA3 compared to control." (PMID 28420874, 2017). "MMP-9 has been extensively investigated in tumor metastasis, including PC metastasis." (PMID 27974694, 2017). "Testing whether TGF-β and pro-inflammatory TNF/IL-1β cytokines cooperate in the regulation of MMP9, we found that MMP9 expression was induced only in tumor cells, while fibroblasts expressed high levels of MMP2." (PMID 28423685, 2017). "In addition, platelets are known to enhance metalloproteinase-9 (MMP-9) secretion, by which platelets promote tumor cell invasion." (PMID 29088839, 2017). "Since myeloid-derived suppressor cells, especially TAMs, promote tumor growth by acting in the local tumor microenvironment, it seems likely that TAMs, MMP9, and sIL-2R all play a role in establishing an immunosuppressive environment that facilitates tumor progression." (PMID 28545581, 2017). "Therefore, the ability of CD44 to localize proteolytically active MMP-9 to the tumor cell surface is important for tumor invasion." (PMID 28326306, 2017). "Moreover Bv8 and metalloproteinase-9 (MMP9) are expressed in the pre-metastatic lung parenchyma and facilitate tumor cells homing." (PMID 29340117, 2017). "Fibroblasts can also enhance tumor infiltration by immune cells producing MMP9." (PMID 28423685, 2017). "Depletion of AP1 components blocks cytokine-mediated induction of MMP9 in tumor cells." (PMID 28423685, 2017). "Furthermore, previous reports indicated that MMP-9 triggers angiogenesis/ invasion while MMP-2 plays vital role in tumor growth." (PMID 28606135, 2017). "A reduction in the levels of the pro-angiogenic factors VEGF (by 6.7-folds, p < 0.01) and MMP-9 (by 5-folds, p < 0.05) was observed in the tumor lysates between the groups receiving the anti-miR-NC and the group receiving anti-miR-146a-5p and stimulated macrophages." (PMID 29354134, 2017). "Furthermore, rottlerin inhibits the markers of angiogenesis (COX-2, VEGF, VEGFR, and IL-8), and metastasis (MMP-2 and MMP-9), thus blocking production of tumorigenic mediators in the tumor microenvironment." (PMID 28423559, 2017). "In addition, MMP9 inhibitor treatment or MMP9 knockdown in 3LL tumor cells completely abolished 3T3-A-EXO-induced 3LL tumor cell invasion in vitro or in vivo, respectively." (PMID 29137230, 2017).